MIR6859-4 (microRNA 6859-4)
Synonyms: hsa-mir-6859-4
Gene: MicroRNA gene on chromosome 16 (17,052 to 17,119, reverse strand). Ensembl gene ENSG00000278739.
Homologues: Paralogues in human: MIR6859-1 (100% identical), MIR6859-2 (100% identical), MIR6859-3 (100% identical).